AVPR1A (arginine vasopressin receptor 1A)
Description:
Receptor for arginine vasopressin. The activity of this receptor is mediated by G proteins which activate a phosphatidyl-inositol-calcium second messenger system. Has been involved in social behaviors, including affiliation and attachment.
Synonyms: V1aR; AVPR1; AVPR V1a
Tractability: Small molecule: an approved drug acts on it; a high-quality ligand is known; it belongs to a druggable protein family. Antibody: its Gene Ontology location is reachable by antibodies, with high confidence; UniProt places it where antibodies can reach, with medium confidence; UniProt predicts a signal peptide or a membrane-spanning region. PROTAC: a small molecule that binds it is known. Other modalities: an approved drug acts on it.
Target class: Family A G protein-coupled receptor; Vasopressin and oxytocin receptor; Short peptide receptor (family A GPCR); Membrane receptor; Peptide receptor (family A GPCR)
Chemical probes: CHEMBL1774023, CHEMBL3416861, ML389, PECAVAPTAN (high quality)
Safety:
Unwanted effects reported when the protein is acted on. In parentheses: how it was acted on, where the effect was seen, and who reports it.
increased blood pressure (Bowes et al. (2012): activation, cardiovascular system, renal; Lynch et al. (2017): activation, acute dosing, renal, central nervous system, cardiovascular)
myocardial fibrosis (Urban et al. (2012): activation, cardiovascular system; Bowes et al. (2012): activation, cardiovascular system, renal)
cardiac hypertrophy (activation; cardiovascular system, renal; source: Bowes et al. (2012))
decreased aggression (inhibition, acute dosing; renal, central nervous system, cardiovascular; source: Lynch et al. (2017))
decreased anxiety (inhibition, acute dosing; renal, central nervous system, cardiovascular; source: Lynch et al. (2017))
decreased body temperature (activation, acute dosing; renal, central nervous system, cardiovascular; source: Lynch et al. (2017))
decreased heart rate (activation; cardiovascular system, renal; source: Bowes et al. (2012))
decreased urinary sodium excretion (inhibition, acute dosing; renal, central nervous system, cardiovascular; source: Lynch et al. (2017))
heart failure (activation; cardiovascular system; source: Urban et al. (2012))
hypertrophy (activation; cardiovascular system; source: Urban et al. (2012))
hyponatraemia (activation; cardiovascular system, renal; source: Bowes et al. (2012))
increased memory (activation, acute dosing; renal, central nervous system, cardiovascular; source: Lynch et al. (2017))
increased urinary sodium excretion (activation, acute dosing; renal, central nervous system, cardiovascular; source: Lynch et al. (2017))
myocardial hypertrophy (activation, chronic dosing; renal, central nervous system, cardiovascular; source: Lynch et al. (2017))
vasoconstriction (activation; cardiovascular system; source: Urban et al. (2012))
water retention in body (activation; cardiovascular system, renal; source: Bowes et al. (2012))
Gene: Protein-coding gene on chromosome 12 (63,142,759 to 63,151,201, reverse strand). Ensembl gene ENSG00000166148.
Subcellular location: Cell membrane
Pathways (Reactome):
Signal Transduction: G alpha (q) signalling events; Vasopressin-like receptors
Disease: Defective AVP does not bind AVPR1A,B and causes neurohypophyseal diabetes insipidus (NDI)
Gene Ontology:
Molecular function: protein binding; vasopressin receptor activity; protein kinase C binding; G protein-coupled peptide receptor activity; G protein-coupled receptor activity; peptide hormone binding; V1A vasopressin receptor binding
Biological process: G protein-coupled receptor signaling pathway; blood circulation; cellular response to hormone stimulus; generation of precursor metabolites and energy; positive regulation of cytosolic calcium ion concentration; positive regulation of vasoconstriction; regulation of systemic arterial blood pressure by vasopressin; transport across blood-brain barrier; calcium-mediated signaling; cellular response to water deprivation; grooming behavior; intracellular pH reduction; maternal aggressive behavior; maternal behavior; myotube differentiation; negative regulation of female receptivity; negative regulation of transmission of nerve impulse; positive regulation of blood pressure; positive regulation of cell growth; positive regulation of cell population proliferation; positive regulation of glutamate secretion; positive regulation of heart rate; positive regulation of prostaglandin biosynthetic process; positive regulation of systemic arterial blood pressure; regulation of blood pressure; and 4 more
Cellular component: endocytic vesicle; endosome; plasma membrane; membrane
Genetic constraint (gnomAD): Loss-of-function variants: 31 observed, 33.09 expected, observed/expected ratio (o/e) 0.94, 90% interval 0.7 to 1.26. The upper end of that interval is the gene's LOEUF score, 1.26, which puts it in group 5 of 6, group 1 being the genes least tolerant of losing a copy. Missense variants: 570 observed, 604.39 expected, observed/expected ratio (o/e) 0.94, 90% interval 0.88 to 1.01. Synonymous variants: 243 observed, 245.17 expected, observed/expected ratio (o/e) 0.99, 90% interval 0.89 to 1.1.
Gene-disease validity (ClinGen):
ClinGen rates the evidence that AVPR1A causes each of these diseases.
autism spectrum disorder (inheritance undetermined): Disputed. A spectrum of developmental disorders that includes autism, and Asperger syndrome.
Homologues: Orthologues: chimpanzee AVPR1A (99% identical), macaque AVPR1A (94% identical), rabbit AVPR1A (87% identical), guinea pig AVPR1A (84% identical), pig AVPR1A (84% identical), rat Avpr1a (83% identical), mouse Avpr1a (83% identical), dog AVPR1A (81% identical), tropical clawed frog avpr1a (64% identical), zebrafish avpr1aa (57% identical), zebrafish avpr1ab (54% identical), Drosophila melanogaster CCAP-R (29% identical). Paralogues in human: AVPR1B (46% identical), OXTR (43% identical), AVPR2 (33% identical), GPR150 (22% identical), CCKAR (20% identical), CCKBR (20% identical), GNRHR (20% identical), HCRTR2 (20% identical), GALR1 (20% identical), NPFFR2 (18% identical), FFAR4 (18% identical), HCRTR1 (17% identical), and 4 more.
Diseases named in the same sentence as AVPR1A in open-access papers:
AVPR1A is named in the same sentence as 75 diseases in open-access papers, as found by Europe PMC text mining. Sharing a sentence is not in itself a finding about the gene and the disease. The quoted sentences say what the papers report.
Anxiety (43 papers, 2008 to 2026). Intense feelings of nervousness, tension, or panic often arise in response to interpersonal stresses. "The finding that BA mice showed decreased levels of anxiety-like behaviour and at the same time the lowest levels of Avpr1a expression suggests an association between life history, anxiety-like behaviour, and Avpr1a expression." (PMID 28821809, 2017). "While there are three receptor subtypes for AVP (V1A, V1B, and V2), the V1A receptor (AVPR1A), has been suggested to play the dominant role in regulating behaviour and is implicated in the modulation of stress, anxiety, and sociability." (PMID 28821809, 2017). "But: This interpretation would be against the findings from genetic animal research showing that knocking out the AVPR1a gene is associated with lower anxiety." (PMID 25852497, 2015). "Thus, as people with a long form of AVPR1a show high levels of anxiety related to the loss of money, they keep the money in either role, distrust the first player, and do not reciprocate in the second player." (PMID 31354450, 2019). "It was investigated whether the resulting four life histories were associated with changes in anxiety-like behaviour, gene expression of selected genes involved in anxiety and stress circuits, and arginine vasopressin receptor 1a (Avpr1a) gene methylation." (PMID 28821809, 2017). "Anxiety and avpr1a expression in the amygdala have been associated in females." (PMID 23641204, 2013). "Finally, we assessed the moderating influence of candidate genes whose level of methylation is associated with the Nr3c1 genotype on anxiety-like behavior: Ank3, Avp, Avpr1a, Avpr1b, Bdnf, Cacna1c, Cyp11b1, Cyp11b2, Fkbp5, Hsd11b1, Igf2, Morc1, Nr3c1, Oxt, Oxtr, Pclo, Slc6a4." (PMID 30655507, 2019). "Although AVPR1A has been associated with several pro-social and affiliative functions, in certain species and within specific contexts, it also mediates processes that might yield anti-social behaviors, including increased aggression and anxiety." (PMID 24924430, 2014). "Genotype for 5-HTTLPR, STin and AVPR1a, and haplotype for HTR2A, DRD4 and OXTR were significantly associated with the duration of behaviours including fear and anxiety." (PMID 37531334, 2023). "In PD prairie voles, female OTR mRNA expression is lower in the medial amygdala and nucleus accumbens while AVPR1a density is higher in the medial amygdala, which is consistent with reduced partner preference and higher anxiety." (PMID 35622681, 2022). "The complexity of the association between maternal behavioral differences and these neuropeptidergic mechanisms is exaggerated by the findings that the administration of an Avpr1a antagonist reduces anxiety/depression-like behavior in preclinical studies." (PMID 33192370, 2020). "For example, AVPR1a has a greater role in modulating anxiety in male mice and blocking this receptor alters social play in males and females in an opposite fashion." (PMID 32587382, 2020). "Impaired social recognition and reduced anxiety behaviors were observed in knockout mice of AVPR1A, while overexpression of AVPR1A in mice led to increased social memory." (PMID 32661244, 2020). "AVPR1A-knockout mouse models show impaired social recognition and decreased anxiety behaviours, while overexpression of AVPR1A in mice resulted in increased social memory." (PMID 21453499, 2011). "Notably, mice experiencing early beneficial and later adverse conditions showed a most pronounced downregulation of Avpr1a expression, accompanied by low anxiety-like behaviour." (PMID 28821809, 2017). "Thus, Avpr1a is a promising candidate gene for future studies on the impact of diverse experiences during life on stress, anxiety and sociability." (PMID 28821809, 2017). "Furthermore, Avpr1a knockout mice displayed reduced anxiety, impaired reciprocal social interaction and decreased social recognition, indicating that the receptor is an important factor in mediating essential social behaviors." (PMID 24924430, 2014).
Anxiety (continued). "Thus, blocking AVPR1A function in rats can actually increase social interactions, most probably by reducing social anxiety." (PMID 24924430, 2014). "For example, people with the SS genotype in AVPR1A RS3 may have exhibited AIA because of the strong effects of arginine vasopressin, which arouses anxiety in social situations, such as when there are reputation concerns." (PMID 37312550, 2023). "The association between AVPR1a and reciprocity cannot be explained by the hypothesis that AVP enhances anxiety related to exploitation by others, as there is no risk of being betrayed by others in this case." (PMID 31354450, 2019).
autism (20 papers, 2005 to 2024). Persistent deficits in social interaction and communication and interaction as well as a markedly restricted repertoire of activity and interest as well as repetitive patterns of behavior. "This is particularly concerning because the main function of the UTR is the regulation of mRNA expression, and the AVPR1A gene is known to be associated with autism." (PMID 38786052, 2024). "Genetic variants of arginine vasopressin receptor 1 A (AVPR1A) gene have also been linked with autism." (PMID 37069342, 2023). "Lastly, as the behavioral characteristics of the parents are not evaluated, there was limitation in examining relationship between AVPR1A variants and behavioral functioning in the context of broader autism phenotype." (PMID 28808521, 2017). "Gene association studies have suggested a link between AVPR1A polymorphisms and autism, and AVPR1A has emerged as a potential pharmacological target for treatment of social cognitive impairments and mood and anxiety disorders." (PMID 24924430, 2014). "In particular, the short allele of RS1 reduced the transcription of AVPR1A, which elevates amygdala activity, thereby leading to social withdrawal that characterizes autism." (PMID 24348454, 2013). "Genetic variation in the promoter region of AVPR1a has been associated with risk for autism, in which social deficits are the core symptom." (PMID 24376401, 2013). "Overall, we observed a single association with AVPR1A in the Irish autism trio collection (rs11174815, corrected P = 0.01)." (PMID 21453499, 2011). "We examined four tagging single nucleotide polymorphisms (SNPs) (rs3803107, rs1042615, rs3741865, rs11174815) and three microsatellites (RS3, RS1 and AVR) at the AVPR1A gene for association in an autism cohort from Ireland." (PMID 21453499, 2011). "Two of these studies have reported that specific alleles of RS3 are overtransmitted in autistic probands, and one of these studies suggests that variation in AVPR1A polymorphisms is predictive of the sociocognitive aspects of autism." (PMID 18573213, 2008). "Nevertheless, despite the dearth of research regarding the molecular mechanisms involved, the AVPR1a promoter-region microsatellites have recently been associated with autism, a disorder whose core symptom is a deficit in social communication." (PMID 16205790, 2005). "Moreover, the chromosomic region 12q14, which includes the AVPR1A locus, was associated with autism through chromosome-wide haplotype analysis." (PMID 32546261, 2020). "The shorter alleles of RS1 were hypothesized to increased susceptibility to autism as a result of decreased AVPR1A expression." (PMID 28808521, 2017). "We hypothesize that alleles of polymorphisms in the promoter region of AVPR1A may differentially interact with certain transcriptional factors, which in turn affect quantitative traits, such as sociality, in children with autism." (PMID 28808521, 2017). "Furthermore, genetic variations in the promoter region of AVPR1A have also been associated with risks for autism, in which social deficits are the major symptoms, as well as autism phenotypes in nonclinical populations." (PMID 28808521, 2017). "In addition to studies involving autism, research in healthy individuals has linked these upstream promoter-region microsatellites of AVPR1A to human social behaviors." (PMID 26295806, 2015). "These aligning results can be interpreted as a functional route for this association, namely that shorter alleles of RS1 lead to decreased AVPR1A transcription, which may proffer increased susceptibility to the autism phenotype." (PMID 21453499, 2011). "Indeed, the AVP gene encodes the ligand for the AVP receptor 1a (AVPR1a) and polymorphisms in this last gene have been shown to be in linkage and in linkage disequilibrium with autism." (PMID 20885821, 2010). "AVPR1A is also associated with autism, an opposite phenotype with poor social communication skills." (PMID 19461995, 2009).
autism (continued). "Moreover, genetic variation at AVPR1A has been reported to be associated with autism." (PMID 21453499, 2011). "Based on prior evidence suggesting a role for AVP in human and animal social cognition, and prior reports of genetic association between variants in vasopressin-related genes and autism, we hypothesized that variants in AVPR1A would be associated with autism in our Irish autism sample." (PMID 21453499, 2011). "Seven genes were in common between the syndromic and non-syndromic autism-related genes and our dataset and included Avpr1a and the glutamate transporter (Slc6a13)." (PMID 32365465, 2020). "Recent studies demonstrated associations between microsatellites (RS1 and RS3) in the promoter region of AVPR1A and autistic disorder and social behavior." (PMID 24348454, 2013). "In the current work we present the results of genetic investigations of the AVPR1A gene in an Irish autism sample." (PMID 21453499, 2011). "Beyond studies linking AVPR1A and various aspects of normal human behavior, there are now three independent studies linking this locus with autism, a disease hallmarked by deficits in social cognition." (PMID 18573213, 2008). "In particular, linkage disequilibrium studies have related the AVP receptor gene AVPR1A to autism." (PMID 32546261, 2020). "The first molecular genetic studies of AVPR1A and human behavior was conducted in families with autism, characterized by impairment in social behavior, and demonstrated transmission disequilibrium between autism and both RS1 and RS3." (PMID 26295806, 2015).
autism spectrum disorder (7 papers, 2014 to 2023). "For instance, the hormone vasopressin gene AVPR1A variants are associated with autism spectrum disorder." (PMID 37628681, 2023). "Genetic polymorphisms in the AVPR1A promoter region have been identified to be associated with susceptibility to social deficits in autism spectrum disorder (ASD)." (PMID 28808521, 2017). "The rs10877969 (T) polymorphism within the AVPR1a gene was the only one to show a statistically significant association with a higher risk of autism spectrum disorders and had an impact on clinical presentation in the ADOS-2 study, primarily in terms of the social affect subscale." (PMID 37190654, 2023). "Recent reports have defined to influence and tolerability of AVPR1A antagonism in autism spectrum disorder." (PMID 36326314, 2022). "The aim of the presented study was to analyze the clinical picture of social cognition deficits in boys with autism spectrum disorders and to relate its elements with the frequency of alleles of selected polymorphisms within the oxytocin receptor (OXTR) and vasopressin receptor 1A (AVPR1A) genes." (PMID 37190654, 2023).
depression (6 papers, 2013 to 2025). "Building on this finding, we subsequently focused on the role of the Avpr1a gene, which is involved in the neuroactive ligand-receptor interaction signaling pathway, in regulating depression." (PMID 40437391, 2025). "Whether low-dose androgen treatment can be used as a clinical approach for treating depression in women, and whether Avpr1a can serve as a target for drug development for female depression, both require further extensive clinical research." (PMID 40437391, 2025). "Importantly, chronic stress-induced depression-like behaviors have been shown to increase AVPR1a expression in the hippocampus." (PMID 40437391, 2025). "Increased reactivity of the anterior cingulate to negatively valenced stimuli is a consistent finding in major depressive disorder; thus modulation of the anterior cingulate via AVPR1a antagonism may well have clinical utility." (PMID 24376401, 2013). "The Avpr1a gene may serve as a new target for the treatment of depression in women." (PMID 40437391, 2025). "Therefore, the increased hypothalamic expression of Avp and Avpr1a could be the manifestation of the depression-like behavior of the WMI dams." (PMID 33192370, 2020). "The observation that human AVPR1A rescued sensorimotor gating deficits in Avpr1a knockout animals provides the first evidence that our humanized mice might be useful for screening drugs targeting AVPR1A for psychiatric disorders and potential therapies for depression and violence." (PMID 24924430, 2014).